RAB5A (RAB5A, member RAS oncogene family)
Diseases named in the same sentence as RAB5A in open-access papers (continued):
Sharing a sentence is not in itself a finding about the gene and the disease.
prostate carcinoma (6 papers, 2012 to 2023). A carcinoma that arises from epithelial cells of the prostate gland. "The expression of RAB5A and EEA1 was significantly reduced in metastatic prostate cancer when compared to primary prostate cancer tissue (P ≤ 0.05)." (PMID 26473288, 2015). "In the current study, quantitation of gene signatures for the early endosomal genes APPL1, EEA1 and RAB5A, and analysis of the endosomal genes MYO1B, PDCD6IP and STX12 in prostate cancer patients expressing PSA ≤ 10 ng/mL, led to patient stratification into high and low-risk recurrence groups." (PMID 26473288, 2015). "NOX2 co-located with Appl1, Rab5A, EEA1 and Rab7 endosome markers in non-malignant cells, but the co-location of NOX2 with these different endosome compartments was significantly increased in prostate cancer cells." (PMID 30459931, 2018). "In addition, in non-malignant cells, both Rab5A and its effector EEA1 were concentrated in the perinuclear region, whereas in prostate cancer cells, these endosomal compartments were found throughout the cytoplasm, with some compartments located toward the cell periphery in cellular extensions." (PMID 30459931, 2018).
breast tumor (4 papers, 2012 to 2025). "MicroRNA-130a targets RAB5A to inhibit the proliferation, invasion and migration of Breast Neoplasms cells." (PMID 33193744, 2020). "We reveal that Rab5a is over-expressed in human breast tumor specimen and contributes MVs generation in those patients." (PMID 29743547, 2018).
Cognitive impairment (4 papers, 2012 to 2025). Abnormal cognition is characterized by deficits in thinking, reasoning, or remembering. "EA could suppress Rab5a‐GTP to promote the transduction of NGF signaling, and enhance the synaptic plasticity of the basal forebrain hippocampal circuit improving cognitive impairment in the early stage of 5 × FAD mice." (PMID 38780008, 2024).
oral cancer (4 papers, 2015 to 2024). "RAB5A is overexpressed in oral cancer and promotes invasion through ERK/MMP signaling." (PMID 35059464, 2022).
atherosclerosis (3 papers, 2013 to 2024). A disease characterized by the build-up of fatty material and calcium deposition in the arterial wall resulting in partial or complete occlusion of the arterial lumen. "So, we established the cell model of atherosclerosis and detected the changes in endothelial cell function caused by overexpression or inhibition of RAB5A expression." (PMID 35059464, 2022). "The function of RAB5A mainly involves endocytosis, exocytosis, and vesicle transport, which can play an important role in the occurrence and development of atherosclerosis." (PMID 35059464, 2022). "Here we focused on five genes (Tgfbr1, Zeb1, Hdac2, Rab5a, and Ets1), which were all identified by miFDR alone, and discussed their potential roles in the context of diesel particle exposure and atherosclerosis." (PMID 24564975, 2013). "RAB5A functions and potential relationships with atherosclerosis have aroused our strong interest." (PMID 35059464, 2022). "This shows the diversity of RAB5A functions, so RAB5A may also promote the development of atherosclerosis by affecting the migration function of endothelial cells." (PMID 35059464, 2022). "So, we speculated that RAB5A can affect atherosclerosis by regulating the proliferation of endothelial cells." (PMID 35059464, 2022). "So, RAB5A may be involved in the pathogenesis of atherosclerosis by changing the proliferation and migration function of endothelial cells through some cytokines and/or signaling pathways, such as the interferon response, Notch signaling pathways, VEGFR2, VE-cadherin, NOS3, and IL-10." (PMID 35059464, 2022). "Targeting RAB5A through IFN might therefore have potential therapeutic effects on atherosclerosis." (PMID 35059464, 2022). "Further research results show that the RAB5A, CTTN, ITGB11and MMP9 can be used to predict atherosclerosis which is verified by GSE28829 and GSE43292." (PMID 35059464, 2022).
HIV-1 infection (3 papers, 2011 to 2015). The type species of lentivirus and the etiologic agent of acquired immunodeficiency syndrome (AIDS). "Rab5A, which coordinates endocytosis and early endosome function, has been reported to regulate the early events of HIV-1 infection in polarized human trophoblasts." (PMID 22072966, 2011).
osteosarcoma (3 papers, 2015 to 2023). A usually aggressive malignant bone-forming mesenchymal neoplasm, predominantly affecting adolescents and young adults. "In this study, RAB11A and RAB5A were also identified as the hub nodes of osteosarcoma." (PMID 36438897, 2022). "miR-301a-3p, RAB5A, and NFKBIA were abnormally expressed in osteosarcoma tissues." (PMID 36438897, 2022).
Sepsis (3 papers, 2021 to 2024). Sepsis is defined as life-threatening organ dysfunction caused by a dysregulated host response to infection. "Rab5a is elevated and is associated with survival in sepsis patients." (PMID 38549133, 2024). "In this study, we demonstrated for the first time, that propofol, acting as an immunomodulating agent, exerts its anti-inflammatory role in sepsis by targeting Rab5a and thereby downregulating membrane TLR4 expression by macrophages." (PMID 38549133, 2024). "Further, we extracted peripheral blood mononuclear cells in sepsis patients and found a significant increase in both Rab5a and cell surface TLR4 expression compared with Health volunteers." (PMID 38549133, 2024). "Knockdown of Rab5a can attenuate the inflammatory response and organ damage in septic mice, suggesting it is a potential target for treating sepsis." (PMID 38549133, 2024). "This informs the potential clinical application of propofol to septic patients and indicates that Rab5a may be a potential therapeutic target against sepsis." (PMID 38549133, 2024). "Our study not only reveals a novel mechanism for the immunomodulatory effect of propofol but also indicates that Rab5a may be a potential therapeutic target against sepsis." (PMID 38549133, 2024). "The correlation between the expression of both factors and the SOFA score of sepsis patients and the high expression of Rab5a in septic non-survivors peripheral blood monocytes further enhanced the clinical relevance of our study." (PMID 38549133, 2024). "Given the importance of these factors to the immune response, therapeutic methods focusing on exploring the possible mechanisms involved in TLR4 trafficking, the regulation of Rab5a expression, and the amount of TLR4 on macrophage surfaces, may be effective strategies for treating sepsis." (PMID 38549133, 2024). "Furthermore, knockout of Rab5a inhibited the expression of proinflammatory cytokines and activation of the JNK and ERK (belong to the MAPK pathway and play a key role in inflammatory response during sepsis) in BMDMs upon LPS treated." (PMID 38549133, 2024). "Moreover, Rab5a and membrane TLR4 expressions were positively associated with the Sequential Organ Failure Assessment score of sepsis patients, and more importantly, the septic non-survivors had significantly increased Rab5a mRNA levels when compared to the septic survivors." (PMID 38549133, 2024). "Moreover, higher expression of Rab5a and surface TLR4 were found in peripheral blood monocytes of patients with sepsis than in the normal control group, and both were correlated with the SOFA score of sepsis patients, with a higher expression of Rab5a found in septic non-survivors." (PMID 38549133, 2024).
tuberculosis (3 papers, 2018 to 2024). A chronic, recurrent infection caused by the bacterium Mycobacterium tuberculosis. "Although not identified previously in MAP resistance/susceptibility studies, the RAB5A gene product was found to be involved in the phagosome and tuberculosis KEGG pathways." (PMID 39062990, 2024). "These 17 pathways also included the phagosome (oas04145) and tuberculosis (oas05152), both of which contain the RAB5A gene and are directly related to MAP infection." (PMID 39062990, 2024). "The second network was tuberculosis (P = 1.03E−03), including ATP6V1H, cathelicidin 1 (CATHL1A), CTSS, ITGB2, myeloid differentiation primary response protein MyD88 (MYD88), and RAB5A." (PMID 30514405, 2018).
lung adenocarcinoma (2 papers, 2013 to 2017). A carcinoma that arises from the lung and is characterized by the presence of malignant glandular epithelial cells. "Some of the genes such as PIK3CA, TAF15, VAPB, Appl1, Rab5a, ARF4, and XIAP in Merged-module activate the PI3K-Akt pathway and are overexpressed in a manner similar to that of EGFR in lung adenocarcinoma." (PMID 23874428, 2013).
amoebiasis (1 paper, 2024). "Within the biological process of amoebiasis, dietary supplementation with PPAH decreased the expression of several genes, including Il6, Serpinb9c, Rab5a, Muc2, Rab7, Lamb1, and Lama1." (PMID 39591294, 2024).
Arthritis (1 paper, 2025). Inflammation of a joint. "Fusobacterium nucleatum causes worsening of arthritis in a mouse model of CIA through the release of FadA-containing outer membrane vesicles, in which FadA triggers synovial inflammation by activating the Rab5a-YB-1 pathway in synovial macrophages." (PMID 40264032, 2025).
breast invasive carcinoma (1 paper, 2024). "Together, these data provide valuable insights into the differential expression patterns of ITGB6, ERBB2, RAB5A, RAB7A, and GDI2 in breast invasive carcinoma." (PMID 39630893, 2024).
cholesteatoma (1 paper, 2022). A pathologic process characterized by the proliferation of keratinizing squamous epithelium resulting in the accumulation of keratin and cells in the middle ear and/or mastoid. "However, in our own middle ear expression dataset from the same patients, all 12 genes were DEGs for cholesteatoma: RTN4, RAB5A, CRYBG1, RGS22, HEPHL1, and SPTLC3 were upregulated, while APBB1IP, BHLHE41, ARID3A, C5AR1, CPT1B, and FAM227A were downregulated." (PMID 36699445, 2022).
laryngeal squamous cell carcinoma (1 paper, 2021). A squamous cell carcinoma that arises from the larynx. "Another study showed that miR-139-3p is significantly downregulated in laryngeal squamous cell carcinoma and that its expression regulates several cancer-related genes, (e.g., RAB5A, ITGB1, FAK, PXN, VEGF, and MMP9)." (PMID 34576110, 2021).
polycystic ovary syndrome (1 paper, 2026). A disorder that manifests as multiple cysts on the ovaries. "In polycystic ovary syndrome (PCOS), a disorder often linked to metabolic and mitochondrial defects in GCs, RAB5A levels are significantly reduced in obese subtypes." (PMID 42066513, 2026).
infection (131 papers, 2008 to 2026). The state of being infected such as from the introduction of a foreign agent such as serum, vaccine, antigenic substance or organism. "Expression of the dominant-negative mutant Rab5a S34N (EGFP-Rab5a S34N), which abrogates the maturation of newly-formed EEs, also resulted in a large decrease in infection, i." (PMID 37578957, 2023). "Altogether, these results indicated that the infectious entry pathway involves the passage of TOSV in Rab5a+ EEs, though the transport to downstream endosomal vesicles is also needed for productive infection." (PMID 37578957, 2023). "Namely, Rab5a was highly recruited at EE organelles before infection, EEA1 was mainly found on dispersed vesicles, whereas Vps34 and Hrs were hardly detectable on endosomes in uninfected cells." (PMID 34575026, 2021). "It was observed that Rab5a protein levels significantly increased starting at 1 h p.i. compared with that for mock infection." (PMID 33504607, 2021). "We also found that knockdown of Rab5a enhanced IFN-λ production compared to that in the controls at an early infection phase (12 and 24 h p.i.)." (PMID 33504607, 2021). "Among infection groups, knockdown of Rab5a significantly alleviated airway inflammation, suggesting that knockdown of Rab5a decreased RSV replication and reduced airway inflammation." (PMID 33504607, 2021). "Confocal microscopic analysis showed that the magnetic beads were enriched at the S. flexneri infection focus colocalizing within Rab5A-positive vesicles, validating the successful internalization of magnetic beads inside S. flexneri IAMs." (PMID 32866204, 2020). "The inhibition of HIV-1 fusion and infection in cells depleted of Rab5A, SNX3 or SNX10 suggests that this virus enters CEM.CCR5 cells via an endocytic pathway." (PMID 30691001, 2019). "For this, MIP- infected cells were immunostained for Rab5 (a marker for early phagosomes) and Rab7 (a marker present on late phagosomes) at different time points after infection." (PMID 29236768, 2017). "We confirmed previous work that the virus was transported through early endosomes in a Rab5A-dependent manner, but additionally showed that MVBs play an important role in productive infection." (PMID 25233119, 2014). "To assess the effect of the Rab family on RSV replication, we depleted Rab1a, Rab2a, Rab4a, Rab5a, Rab6a, Rab7a, Rab8a, Rab9a, and Rab11a by treating A549 cells with specific siRNAs (or control siRNA) for 24 h, followed by infection with purified RSV A2 and incubation for another 36 h." (PMID 33504607, 2021). "Because the Rab5a expression level was increased at an early infection time and viral and host factors are involved in early infection, we assessed the effect of Rab5a on viral early life cycle procedures (viral binding and endocytosis) in RSV infection of A549 cells." (PMID 33504607, 2021). "In addition to LAMP-1, other regulators could also potentially contribute to regulate the fusion; Rab5A and Rab22A have been found to be associated with the stimulation of the maturation of phagosomes containing either Listeria or Mycobacteria during early infection." (PMID 30186773, 2018). "Indeed, we found that Rab5a is specifically recruited on Leishmania-PV after 24 h of infection in human macrophages." (PMID 28650977, 2017). "However, more than 74% inhibition of parasite load was observed in Rab5a knockdown human macrophages in comparison to control cells after 96 h of infection." (PMID 28650977, 2017). "However, our results have also shown that Leishmania containing PV in mouse macrophages does not recruit and retain Rab5a after 24 h of infection whereas Leishmania containing PV in mouse macrophages is shown to recruit Rab5 in early time point of infection." (PMID 28650977, 2017).
infection (continued). "To examine whether passage through the endosomal compartments was required for infectivity, we first assessed TOSV internalization and infection in A549 cells transfected with DNA plasmids to express a constitutively-active mutant of Rab5a tagged with EGFP (EGFP-Rab5a Q79L)." (PMID 37578957, 2023). "Interestingly, EC (ATP1B3) exhibited higher expression of phagocytosis-related genes in TNBC patients, RAB5A and EEA1, indicating these patients could be more susceptible to infection." (PMID 35265720, 2022). "Expression of Rab5a S34N, which inhibits EE maturation and homotypic EE fusion, reduced TOSV intracellular trafficking and infection." (PMID 37578957, 2023). "To investigate the dynamic Rab5a expression in RSV-infected BALB/c mice, we first measured the Rab5a protein level at different times of infection." (PMID 33504607, 2021). "For instance, EspF recruits clathrin, AP2, early (Rab5a and EEA1) and recycling (Rab4a, Rab11a, Rab11b, FIP2, Myo5b) endocytic proteins to sites of infection." (PMID 31947656, 2020). "We therefore investigated the T3SS dependence of the distribution of clathrin endocytic (CHC, AP2-α, Rab5a and EEA1) and recycling [Rab11a, Rab11b, Rab25, Myosin 5b (Myo5b)] components upon EPEC infection of polarized MDCK cells." (PMID 31242273, 2019). "We next asked if depletion of Rab5A, SNX3 or SNX10 in CEM.CCR5 cells inhibits HIV-1 fusion and infection by modulating the virus uptake." (PMID 30691001, 2019). "The requirement for Rab5A, SNX3 and SNX10 for efficient HIV-1 fusion and infection in CEM.CCR5 cells suggests that endocytosis plays a role in productive entry into these cells." (PMID 30691001, 2019). "We performed a screen utilizing a direct virus-cell fusion assay as readout and identified several host proteins involved in endosomal trafficking/maturation, including Rab5A and sorting nexins, as factors regulating HIV-1 fusion and infection." (PMID 30691001, 2019). "We show that type-III secreted components prompt the recruitment of clathrin (clathrin and AP2), early (Rab5a and EEA1) and recycling (Rab4a, Rab11a, Rab11b, FIP2, Myo5b) endocytic machineries to peripheral plasma membrane infection sites." (PMID 31242273, 2019). "Shortly after infection, the ASFV virions enter into cells via clathrin-mediated endocytosis (CME) and the capsid protein p72 can be detected in early endosomes colocalizing with specific markers such as EEA1 and Rab5A." (PMID 39024394, 2024). "Interestingly, while Tfn, Rab5a and EEA1 showed very low levels of clustering at infection sites, Rab11a displayed significantly higher clustering at these sites." (PMID 31242273, 2019). "In addition, we also found that latex beads containing phagosomes are clearly separated from Rab5a and EEA1 positive Leishmania-PV in macrophages after 24 h of infection." (PMID 28650977, 2017). "Our results showed that infection in Rab5a knockdown macrophages is not compromised as similar numbers of parasites are observed in both Rab5a knockdown and control cells at 0 h." (PMID 28650977, 2017). "Furthermore, the sensitivity of HIV-1 fusion and infection to Rab5A knockdown but not to Rab7A knockdown suggests that HIV-1 may tend to fuse in early endosomes of CEM cells." (PMID 30691001, 2019). "D. discoideum Rab5A has not been investigated thus far, but it was identified as a part of the LCV (Legionella-containing vacuole), a special type of phagocytic vesicle that forms during the infection with bacteria Legionella pneumophila." (PMID 38263885, 2024).